MUC1 (mucin 1, cell surface associated)
Diseases named in the same sentence as MUC1 in open-access papers (continued):
Sharing a sentence is not in itself a finding about the gene and the disease.
tumor (continued). "The combination of M-M and CpG 1826 significantly inhibited MUC1-expressing B16 cell growth and prolonged the survival of tumor-bearing mice." (PMID 29558459, 2018). "The study provides promising data for future development of a novel MUC1-targeted nanocarrier for direct delivery of imaging agents or drugs into the tumor microenvironment." (PMID 29685122, 2018). "Using a MUC1 vaccination strategy along with a type 1 DC polarizing cocktail, they were able to reduce Tregs and enhance survival in MUC1KrasPTEN tumor-bearing mice." (PMID 30049987, 2018). "The recognition of MUC1-ST by siglec-9 on tumor-infiltrating macrophages was shown to initiate inhibitory immune pathways mediated by MEK-ERK signaling." (PMID 30538706, 2018). "It has been demonstrated that MUC1 is involved in oncogenic processes and enhances tumor initiation and progression." (PMID 30405607, 2018). "The studies in this work confirmed that Muc1-Bi bispecific antibodies have potent anti-tumor activity against Muc1 positive tumor cells." (PMID 29357376, 2018). "Within tumor tissue alone, MUC1 and KIT exhibited increased expression in patients with a low CRP compared to those with a CRP ≥5 mg/L." (PMID 30016964, 2018). "The aptamer used was the anti-MUC1 aptamer, able to specifically recognize the MUC1 receptor that is over-expressed in different tumor cell lines." (PMID 30384431, 2018). "Overexpression of human MUC1 in the mouse mammary gland drives tumor formation by potentiating EGF-dependent activation of MAP kinase signaling pathways." (PMID 29423058, 2018). "Three percent of the tumor samples had MUC1 expression in ≥75% of tumor cells, 9.1% of samples had 74–50% staining, 48.5% of samples had 49–11% staining and 9.1% of samples had no expression." (PMID 29987260, 2018). "MUC-1 expression was confirmed by immunostaining a sample of the disseminated tumor, which encouraged us to use MUC-1 long-peptide vaccine as the tumor-associated antigen." (PMID 30219954, 2018). "Clearly, these data indicate that the molecular mechanisms activating expression of MYC are different in cells derived from different tumours (see MUC1, MYC and MDSCs above)." (PMID 29784646, 2018). "In tumor settings MUC1 loses its polarity and normal pattern of glycosylation to expose GalNAc (Tn) residue." (PMID 29857542, 2018). "On the other hand, MUC1 acts as a tumor suppressor as it prevents aberrant upregulation of genes related to cell acquisition of malignant phenotype." (PMID 29680855, 2018). "It has been suggested that secreted MUC1 is a ligand for MUC1/Y, which initiates signaling events and changes in cell morphology in tumor cells." (PMID 30405607, 2018). "A great performance in terms of tumor accumulation (20% value at 90 min) was also obtained by using radiolabeled MUC1 aptamer-capped mesoporous silica NPs in the same animal model of TNBC." (PMID 30428522, 2018). "MUC1 drives tumor progression in multiple tumor types through activating important oncogenic proteins including EGFR, β‐catenin, NF‐κB, PKM2, and other pathways." (PMID 30024105, 2018). "The bispecific antibody binds to CD3 on the CIK and MUC1 on tumor cells, crosslinking the CIKs and tumor cells promoting effective tumor cell lysis." (PMID 30249178, 2018). "Because of the tumor promotional microenvironments and reduced apoptosis, MUC1-CD delays PMI process and results in atypical phenotype in multiparous mice mammary." (PMID 29423058, 2018). "Interest in MUC1-based cancer immunotherapy stems from this marker's aberrant glycosylation in tumor cells due to truncated, highly sialylated O-glycans that occur at up to five potential sites on each of MUC1's 20 amino acid tandem repeat sequence." (PMID 30450094, 2018).
tumor (continued). "Some recently initiated clinical trials are taking on board the novel findings emerging from work on the structure and function of MUC1 and its interaction with the tumour environment and immune effector cells." (PMID 29784646, 2018). "It seemed that suppression of MUC1 expression indirectly affected activity and proliferation T cells in the tumor." (PMID 29342882, 2018). "Following CAR optimization with tripartite endodomains and high affinity screening for effective ScFv fragments, MUC1-CAR T cells showed significant delays in tumor growth in mouse xenograft models." (PMID 30031396, 2018). "Phase II studies utilizing M7824, including a study combining M7824 and a therapeutic cancer vaccine targeting prostate specific antigen (PSA) or carcinoembryonic antigen (CEA) plus mucin 1 (MUC1), are currently planned or ongoing in multiple tumor types." (PMID 29721396, 2018). "After tumor challenge, mice immunized with M-M + CpG 1826 developed the highest levels of sera anti-MUC1 antibody titers compared with other groups." (PMID 29558459, 2018). "The binding of siglec-9 to MUC1 has also been reported to increase the growth of the tumour cell via recruitment of β-catenin." (PMID 29903935, 2018). "By characterizing nine different GBCCLs and several fresh tumor tissues, we found that they expressed some tumor-associated antigens such as CEA, MUC-1, CA19-9, Erb2, Survivin, and several carcinoembryonic antigens." (PMID 29600445, 2018). "It is becoming apparent that MUC1 expressed by cancer cells can affect the phenotype and function of immune cells in the tumour microenvironment inhibiting their function." (PMID 29784646, 2018). "To study the clinical significance of WFA-sialylated MUC1, we compared levels in samples among different primary tumor sites, cancer stages, and tissue types." (PMID 27358229, 2017). "Confocal microscopy experiments proved that, while anti-MUC1 antibody interacted only with the protein target at the surface of the spheroid, Cy3-MUC1-aptamer was able to penetrate inside these 3D tumour models and internalize into the cancer cells." (PMID 29261171, 2017). "Subsequently, multi-marker RT-PCR analysis was used to detect tumor-associated transcripts, including KRT19, MUC1, EpCAM, CEACAM5, and BIRC5." (PMID 28626429, 2017). "Splenocytes from cured mice showed consistent production of IFN-γ cytokine upon in vitro stimulation with Renca-MUC1 cell lysates confirming that the treatment of radiation and vaccine induced T cells specific to the tumor cells." (PMID 28116088, 2017). "Tumor forms of MUC1 are chemotactic to immature dendritic and inhibit their ability to stimulate type 1 helper T cell responses." (PMID 29285251, 2017). "Mice treated with the sequence of radiation followed by vaccine (Schedule 1) showed a higher cure rate (24%) and demonstrated specific tumor immunity when rechallenged with Renca-MUC1." (PMID 28116088, 2017). "We have recently shown that antigen transfer to DCs mediated by tumor MVs is crucially relevant for cross-presentation of tumor-glycosylated antigens such as MUC1." (PMID 28993771, 2017). "Meanwhile, MUC-1 is known to be expressed in the UB of the developing kidney, which was differentially expressed in the triphasic tumours in our microarray data." (PMID 29040332, 2017). "Altered cellular metabolism is one of the hallmarks of cancer, and recently a functional role of MUC1 in tumorigenesis was highlighted by the observation that MUC1 plays a key role in tumor metabolism." (PMID 28464016, 2017). "Looking at a comparison between a normal epithelial cell and a cancer cell, one can distinguish that the tumor cell has lost its polarity where the and the increased expression of the hypoglycosylated form of MUC1." (PMID 29250208, 2017). "The PEG-modified probe preferentially accumulated in MUC1 positive cells (e.g., MCF-7) showing improved contrast for MUC1 positive tumours in vivo." (PMID 29261171, 2017).
tumor (continued). "When mice were treated with radiation and empty MVA, a few mice (3 out of 20 mice) were cured and rejected Renca-MUC1 tumor challenge indicating some tumor immunity, probably directed against vaccinia antigens." (PMID 28116088, 2017). "Serum WFA-sialylated MUC1 levels in BTC/IhCC varied little by pathological cancer stage or tumor tissue type, with similar levels between early and advanced stages and between well-differentiated and undifferentiated carcinomas." (PMID 27358229, 2017). "In future studies, comparison between serum WFA-sialylated MUC1 levels and surgically obtained tumor samples is needed to evaluate the reproducibility cut off value of WFA-sialylated MUC1." (PMID 28325920, 2017). "Taken together, these results suggest that CS-induced MUC1 overexpression, redistribution, phosphorylation, and protein–protein interactions promote lung carcinogenesis and tumor metastasis." (PMID 29186029, 2017). "Responding mice were immune to challenge with Renca-MUC1 cells, indicating the induction of specific tumor immunity." (PMID 28116088, 2017). "MUC1 was expressed primarily in the apical membrane and occasionally in the cytoplasm of tumor cells." (PMID 28415560, 2017). "In 1989, a cell surface glycoprotein of the mucin family, MUC1, which is expressed in tumors in an aberrantly glycosylated form, was described as a tumor antigen that can be recognized by cytotoxic T cells." (PMID 29312332, 2017). "Recent studies suggest that MUC1 plays a role in modulating cancer cell metabolism and thereby supports tumor growth." (PMID 28464016, 2017). "We used the MUC1 protein as a model TAA since it is one of the most commonly expressed protein on tumor of epithelial origin and is the target of many immunotherapeutic vaccination protocols." (PMID 28679396, 2017). "The differentially expressed genes in triphasic tumours relative to blastemal tumours included genes published as potential UB/CD markers: MUC1, PKHD1, KRT7, CDH1, and LIF." (PMID 29040332, 2017). "A large number of studies have shown that the tumor antigens survivin and MUC1 are highly expressed in variety of tumors, especially lung cancer." (PMID 29268708, 2017). "The determination of the level of MUC1 protein in the serum has been exploited as a measure of tumor burden and changing levels, as a reflection of the response to therapy." (PMID 28817726, 2017). "Serum WFA-sialylated MUC1 was associated with HCC recurrence on univariate analysis, along with tumor size and DCP levels." (PMID 28325920, 2017). "Immunity to rechallenge with Renca-MUC1 cells suggested the generation of specific T- cells against tumor antigens." (PMID 28116088, 2017). "In fact, DCs appear more efficient in cross-priming antigens carried by MVs than the soluble antigens and only when carried by MVs, large tumor glycosylated antigens as MUC1 are cross-presented and CD8+ T cell responses are activated." (PMID 28993771, 2017). "MUC-1 has a correlation with the increase in tumor cells related to breast, ovarian, colon, lung, and prostatic cancers." (PMID 29250208, 2017). "We designed a standard using protein lysate isolated from a MUC1-expressing tumor cell line (KCM), which was also used to generate the TAB004 antibody." (PMID 28680538, 2017). "Immunohistochemical analysis of survivin and MUC1 expression in the tumor biopsies prior to vaccination were both positive in all patients." (PMID 29268708, 2017). "In order to clarify the physiological role of phagosomal alkalinization induced by tumor MVs in MUC1 antigen cross-processing, the intracellular re-localization of MUC1 was analyzed by immunofluorescence in DCs pulsed with MVsAsc, treated or not with DPI." (PMID 28993771, 2017). "MUC1, a heavily glycosylated large glycoprotein, is frequently over-expressed on the cell surface of glandular epithelial cells in a variety of tumor types, including NSCLC." (PMID 29268708, 2017).
tumor (continued). "We have previously reported that lung ADC cells expressed high levels of KL-6/MUC1 and that an anti-KL-6 mAb induced capping of MUC1, thereby interfering with its anti-adhesion function and inhibiting tumor proliferation." (PMID 28403862, 2017). "As patients included in the TIME trial had different percentages of MUC1 expression within their tumor cells, we evaluated the diversity of T cell specific response to MUC1 in subgroups of patients with different levels of MUC1 expression." (PMID 28923084, 2017). "The increased colon inflammation and tumor incidence detected in MUC1.Tg mice compared to WT mice suggested a key role of human MUC1 in controlling inflammation-driven cancer." (PMID 29285251, 2017). "On multivariate analysis, WFA-sialylated MUC1 (HR = 1.95, 95% CI: 1.15–3.29, p = 0.01) and tumor size (HR = 1.72, 95% CI: 1.04–2.82, p = 0.03) were independent predictors of HCC recurrence." (PMID 28325920, 2017). "Of the 61 tumor biopsy specimens, sialylated MUC1- and CK19-positive immunohistochemical staining was positive in 16% (10/61) and 10% (6/61), respectively." (PMID 28325920, 2017). "In normal goblet cells, AGR2 is required for folding and processing of secreted (MUC5AC) and membranous mucins (MUC1, MUC2, MUC5B;) which have also been implicated in various tumor-promoting processes." (PMID 29267283, 2017). "To examine the contribution of the MUC1/EGFR–ABCB1 axis to tumor chemoresistance, we treated the HeLa229/shCTL tumor-bearing mice with PTX in combination with verapamil or erlotinib." (PMID 28796259, 2017). "The MVA–MUC1–IL-2 cancer vaccine construct was successfully tested clinically in patients with MUC1-overexpressing malignancies in order to induce a specific anti-tumor immune response." (PMID 28116088, 2017). "AuNPs were used as labels and foundation which carries the HO aptamer and the enzyme, forming a tracing tag to ultrasensitively detect mucin 1 protein (MUC1), a well-known tumor marker existing in various malignant tumors." (PMID 29039742, 2017). "Responding mice which showed complete tumor regression were immune to challenge with Renca-MUC1, indicating that these mice developed specific tumor immunity." (PMID 28116088, 2017). "Based on these data, it is clear that KL-6/MUC1 plays an important role in tumor cell growth, proliferation, and metastasis." (PMID 28403862, 2017). "The presence of human MUC1 aggravates colonic inflammation and increases tumor initiation and progression in an in vivo AOM/DSS mouse model of colitis-associated cancer (CAC)." (PMID 29285251, 2017). "Overexpression of MUC1 is more pronounced at the deepest tumor invasive portion, lymphatic and venous invasion, and lymph node and liver metastasis." (PMID 28153010, 2017). "In A549 xenografts, MUC-1 expression in tumor cells was inhibited by citrate and cisplatin treatment individually, and the combination of citrate and cisplatin further reduced MUC-1 expression." (PMID 28674429, 2017). "When samples were classified by tumor tissue type, WFA-sialylated MUC1 showed little difference in diagnostic sensitivity compared to CA19-9, but demonstrated significantly higher diagnostic sensitivity in comparison to CEA." (PMID 27358229, 2017). "In mouse models of IBD and CAC, we have previously detected extensive accumulation of pro-inflammatory cell populations in MUC1.Tg mice at the sites of inflammation as well as in the tumor microenvironment." (PMID 29285251, 2017). "Further pieces of evidence suggest that efficacious antigen cross-priming of the MUC1 antigen carried by the tumor MVs results from the early signaling induced by MV internalization and the function of the antigen-processing machinery of DCs." (PMID 28993771, 2017). "In conclusion, serum WFA-sialylated MUC1 level was associated with HPC/biliary features in HCC and with a high incidence of tumor recurrence." (PMID 28325920, 2017).
tumor (continued). "In the current study, we also demonstrated evidence of the abscopal effect of tumor irradiation upon combination MVA- MUC1-IL-2 vaccine." (PMID 28116088, 2017). "To enhance the therapeutic effect of TG4010, i.e., MVA-MUC1-IL-2 cancer vaccine, we have tested the efficacy of tumor irradiation for the treatment of Renca murine RCC cells transfected with MUC1." (PMID 28116088, 2017). "Efficient tumor elimination also utilizes TACA-specific CD8+ cytotoxic T cells, particularly since tumor-shed, aberrantly glycosylated MUC1 can interfere with tumor targeting by anti-MUC1 antibodies." (PMID 27472370, 2016). "We tabulated that 65% of tumor specimens demonstrated high expression of MUC1, whereas 35% displayed a relatively lower MUC1 expression." (PMID 27276704, 2016). "That MUC1 affects gene expression is well established; however, the mechanism by which MUC1 regulates transcription and affects tumor progression is not fully understood." (PMID 27220889, 2016). "Greater efficacy was achieved by continuing vaccination into the tumor-bearing period, demonstrating the T-cells’ requirement for stronger re-stimulation than that provided by MUC1-expressing tumors alone." (PMID 26788922, 2016). "223Ra significantly enhanced T cell-mediated lysis of each tumor type by CD8+ CTLs specific for MUC-1, brachyury, and CEA tumor antigens." (PMID 27893426, 2016). "During these studies, one xenograft (MUC-1) showed particular engraftment properties and sustained tumor growth." (PMID 27764813, 2016). "As the patient had been treated with EDP-M followed by metastatic spread including the tumor sample, which had been used for the MUC-1 xenograft we sought to investigate the therapeutic responsiveness in comparison to NCI-H295R cells." (PMID 27764813, 2016). "We found that this hypoglycosylated tumor form of MUC1 is also overexpressed during chronic inflammation and in premalignant lesions that progress to tumors." (PMID 27754373, 2016). "The tumor-associated antigen MUC1 is over-expressed by about three-fourths of all lethal human cancers, and was recently ranked number two by the NCI among all known tumor-associated antigens for meriting fast-tracked clinical prioritization." (PMID 26788922, 2016). "Although overexpression of MUC1 gene is typical for both normal epithelium and epithelial tumour cells, its isoform Y is considered tumour-specific." (PMID 27803125, 2016). "Such tumor escape mechanisms were also observed in the subset of B16.MUC1 challenged mice which ultimately developed progressive tumors and in Panc02.MUC1." (PMID 26788922, 2016). "There have been limited attempts to use anti-MUC1 antibodies in therapy as very few mouse antibodies have been identified with tumor specificity." (PMID 27545199, 2016). "Previous publications have reported impact of MUC1 expression on tumor progression and also on survival." (PMID 27298226, 2016). "Changes of MUC1 cell surface localization in response to galectin-3 binding also induce cancer cell homotypic aggregation and the formation of circulating tumor emboli, thus preventing the cells from undergoing anoikis and prolonging the cell survival." (PMID 27066458, 2016). "Peptide vaccination with CpG was highly effective for reversing MUC1 tolerance in MUC1.Tg mice, but was completely ineffectual for protecting against tumor challenges initiated after vaccinations were completed." (PMID 26788922, 2016). "By promoting focal adhesion assembly, MUC1 promotes also tumor cell growth and facilitates metastasis." (PMID 27754373, 2016). "Overexpression and aberrant glycosylation of MUC1 on tumor cells influences many critical steps in tumor initiation, progression, and metastasis as well as in tumor immunosurveillance." (PMID 27754373, 2016). "In four bone metastases examined, MUC1 was detected heterogeneously among patients, in different tumor masses within the same tissue, and among different cancer cells within the same tumor mass." (PMID 27825118, 2016).